MYO10 (myosin X)
Description:
Myosins are actin-based motor molecules with ATPase activity. Unconventional myosins serve in intracellular movements. MYO10 binds to actin filaments and actin bundles and functions as a plus end-directed motor. Moves with higher velocity and takes larger steps on actin bundles than on single actin filaments. The tail domain binds to membranous compartments containing phosphatidylinositol 3,4,5-trisphosphate or integrins, and mediates cargo transport along actin filaments. Regulates cell shape, cell spreading and cell adhesion. Stimulates the formation and elongation of filopodia. In hippocampal neurons it induces the formation of dendritic filopodia by trafficking the actin-remodeling protein VASP to the tips of filopodia, where it promotes actin elongation. Plays a role in formation of the podosome belt in osteoclasts. [Isoform Headless]: Functions as a dominant-negative regulator of isoform 1, suppressing its filopodia-inducing and axon outgrowth-promoting activities. In hippocampal neurons, it increases VASP retention in spine heads to induce spine formation and spine head expansion (By similarity).
Synonyms: KIAA0799; MyoX
Tractability: Small molecule: a structure with a bound ligand is known. Antibody: its Gene Ontology location is reachable by antibodies, with high confidence; UniProt places it where antibodies can reach, with medium confidence; the Human Protein Atlas places it where antibodies can reach. PROTAC: ubiquitination databases record sites on it.
Gene: Protein-coding gene on chromosome 5 (16,661,907 to 16,936,288, reverse strand). Ensembl gene ENSG00000145555.
Subcellular location: Cytoplasm, cytosol; Cell projection, lamellipodium; Cell projection, ruffle; Cytoplasm, cytoskeleton; Cell projection, filopodium tip; Cytoplasm, cell cortex; Cell projection, filopodium membrane
Subcellular location (Human Protein Atlas): Cytosol; Plasma membrane; Nucleoli rim
Pathways (Reactome):
Developmental Biology: Netrin-1 signaling
Disease: FCGR3A-mediated phagocytosis
Immune System: Regulation of actin dynamics for phagocytic cup formation
Gene Ontology:
Molecular function: protein binding; spectrin binding; actin filament binding; microfilament motor activity; phosphatidylinositol-3,4,5-trisphosphate binding; plus-end directed microfilament motor activity; ATP binding; cytoskeletal motor activity; cytoskeletal protein binding; protein-containing complex binding
Biological process: regulation of cell shape; regulation of filopodium assembly; cytoskeleton-dependent intracellular transport; signal transduction
Cellular component: cytosol; plasma membrane; filopodium; filopodium tip; cell cortex; cytoskeleton; filopodium membrane; lamellipodium; myosin complex; neuron projection; neuronal cell body; ruffle
Genetic constraint (gnomAD): Loss-of-function variants: 123 observed, 227.16 expected, observed/expected ratio (o/e) 0.54, 90% interval 0.47 to 0.63. The upper end of that interval is the gene's LOEUF score, 0.63, which puts it in group 2 of 6, group 1 being the genes least tolerant of losing a copy. Missense variants: 2,302 observed, 2,547.6 expected, observed/expected ratio (o/e) 0.9, 90% interval 0.87 to 0.94. Synonymous variants: 1,069 observed, 1,000.9 expected, observed/expected ratio (o/e) 1.07, 90% interval 1.01 to 1.12.
Homologues: Orthologues: chimpanzee MYO10 (99% identical), macaque MYO10 (99% identical), rabbit MYO10 (95% identical), rat Myo10 (95% identical), mouse Myo10 (95% identical), pig MYO10 (93% identical), dog MYO10 (92% identical), guinea pig MYO10 (86% identical), tropical clawed frog myo10 (81% identical), zebrafish myo10 (67% identical). Paralogues in human: MYO15A (28% identical), MYO7A (27% identical), MYO7B (25% identical), MYH7 (20% identical), MYH6 (20% identical), MYH8 (20% identical), MYH2 (20% identical), MYH1 (20% identical), MYH3 (20% identical), MYH4 (20% identical), MYH13 (20% identical), MYH10 (19% identical), and 32 more.
Diseases named in the same sentence as MYO10 in open-access papers:
MYO10 is named in the same sentence as 47 diseases in open-access papers, as found by Europe PMC text mining. Sharing a sentence is not in itself a finding about the gene and the disease. The quoted sentences say what the papers report.
breast carcinoma (20 papers, 2013 to 2025). "As a critical regulator of filopodia, myosin X is elevated in breast cancer, and its expression correlates with poor prognosis." (PMID 41011506, 2025). "Third, breast cancer progression in mice was shown to be inhibited by Myo10 depletion and accelerated by Myo10 overexpression." (PMID 40440343, 2025). "High expression of MYO10 contributes to the tumor invasion and migration of breast cancer, prostate cancer, and colorectal cancer." (PMID 36645718, 2023). "Aberrant levels of MYO10 were observed in breast cancer as well as squamous cell carcinoma of the lung." (PMID 35478939, 2022). "In the broader context of carcinomas, elevated expression of myosin X and myosin 1e were shown to promote the aggressiveness of breast cancer." (PMID 33801718, 2021). "Consistently, MYO10 depletion inhibits migration and invasion of breast cancer and melanoma cells in vitro and attenuates colonization of the lungs by tumor cells in vivo." (PMID 33670106, 2021). "MYO10 is necessary for the growth, migration, and invasion of breast cancer cells in vivo and in vitro." (PMID 32670437, 2020). "The expression level of MYO10 increases in breast cancer, lung adenocarcinoma, non-small-cell lung cancer (NSCLC), metastatic prostate cancer cell lines, and prostate cancer tissues." (PMID 32670437, 2020). "In human melanoma, increased expression of Myo10 decreases patient survival, which is the same effect observed in breast cancer." (PMID 29993000, 2018). "MiR-340 was also reported to be involved in suppressing migration and invasion by targeting MYO10 or c-Met in breast cancer cells." (PMID 29137386, 2017). "Recent observations elucidated that elevated expression of MYO10 contributes to aggressiveness and metastasis in breast cancer." (PMID 25749519, 2015). "In a recent study of breast cancer with poor prognosis, expression of MYO10 is significantly increased in patients with breast cancer." (PMID 23628382, 2013). "In this dataset, breast cancer cells expressing a CTRL shRNA or a shRNA targeting the filopodial protein MYO10 were allowed to migrate either beneath a collagen gel or within standard media (data describing the migration behavior of these cells in standard media was previously reported here)." (PMID 39116189, 2024). "In breast carcinoma samples, MYO10 predominantly accumulates at the invasive tumor edges." (PMID 33670106, 2021). "MYO10 expression was found elevated in various tumors, most notably in breast cancer and melanoma." (PMID 33670106, 2021). "MYO10 cannot support breast cancer cell migration when it lacks the integrin-binding domain." (PMID 32670437, 2020). "Migration in breast cancer can be suppressed by targeting MYO10." (PMID 31213036, 2019). "Therefore, MYO10 expression correlates with both Src expression and Src activity in breast cancer patient samples." (PMID 27910855, 2016). "Whether MCU expression is connected with MYO10 or c-Met in breast cancer remains unraveled." (PMID 29137386, 2017).
breast tumors (5 papers, 2016 to 2023). "One study found that in breast tumors, high levels of MYO10 increased the presence of interferon (INF)." (PMID 37214088, 2023). "A recent study showed that MYO10 mRNA expression was significantly higher in breast tumors with mutant p5328." (PMID 29993000, 2018).
colorectal cancer (4 papers, 2019 to 2023). A primary or metastatic malignant neoplasm that affects the colon or rectum. "Previous studies demonstrated that both Myosin X and Trio interact with DCC (deleted in colorectal cancer), a receptor of Netrin-1, and the Rac1 activation elicited by Netrin-1 is lost in the Trio-deficient cortex." (PMID 34914033, 2022). "We found a positive correlation (r = .222 in PanCancer datasheet; r = .318 in Colorectal Cancer project, *p < .001) between KITENIN and Myo10 expression in colorectal adenocarcinoma in TCGA." (PMID 35853101, 2022). "Filopodia-inducing Myo10 is implicated in axon guidance and mice lacking the Myo10 cargo protein DCC (deleted in colorectal cancer) have severe commissural defects, whereas MRI (magnetic resonance imaging) of isolated brains revealed intact commissures in Myo10tm2/tm2 mice." (PMID 30679680, 2019).
melanoma (4 papers, 2018 to 2025). A malignant, usually aggressive tumor composed of atypical, neoplastic melanocytes. "We also determined that elevated expression of the MYO10 gene was associated with inferior survival outcomes in melanoma patients and Myo10 expression increased in human melanoma." (PMID 29993000, 2018). "First, the depletion of Myo10 in a mouse model of melanoma was shown to reduce melanoma development and metastasis and to extend medial survival time." (PMID 40440343, 2025). "Together, we uncovered for the first time that Myo10-induced protrusions drive melanoblast migration and melanoma initiation and metastasis." (PMID 29993000, 2018). "To confirm Myo10 protein expression in human melanoma, we stained randomly selected tissue samples of diagnosed benign nevi (n = 5) and malignant melanoma (n = 9) archived in the SkinPath Laboratory of Boston University School of Medicine." (PMID 29993000, 2018). "To investigate the role of Myo10 in human melanoma, we first analyzed the expression of MYO10 mRNA in human skin, benign nevi, and melanoma samples by in silico analysis of Oncomine datasets." (PMID 29993000, 2018). "MYO10 mRNA was significantly higher in melanoma than in normal skin in the Riker melanoma data set and in the Talantov melanoma data set." (PMID 29993000, 2018). "Box-and-whiskers plots demonstrated that Myo10 expression was significantly higher in melanoma lesions than in nevi, consistent with the data of MYO10 mRNA expression." (PMID 29993000, 2018). "To study Myo10 function in melanoma metastasis, we performed necropsy of Tyr-CreER/PtenKO/BrafCA/Myo10KO and Tyr-CreER/PtenKO/BrafCA/Myo10WT mice when tumor volumes reached ~1,000 cm3." (PMID 29993000, 2018). "In summary, we propose a Myo10-mediated LP induction model in melanoblast migration and melanoma induction and metastasis." (PMID 29993000, 2018). "Log-rank (Mantel-Cox) test of survival plots revealed a significant difference between the Myo10WT and KO genotypes under the genetic background of Tyr-CreER/PtenKO/BrafCA, evidence of Myo10’s role in melanoma progression." (PMID 29993000, 2018). "Knockdown of Myo10 (Myo10kd) in B16F1 mouse melanoma cell lines decreased lung colonization after tail-vein injection." (PMID 29993000, 2018). "Consistent with this hypothesis, melanoma cells migrating in 3D collagen matrices extend filopodia from their pseudopods in a Myo10-dependent manner." (PMID 37703992, 2023). "Here, we investigate the role of Myo10 in melanocyte lineage and melanoma induction." (PMID 29993000, 2018). "Nonetheless, nothing is known about the function of Myo10 in melanoma." (PMID 29993000, 2018). "We speculate that Myo10 plays an important role not only in melanoblast migration but also in melanoma metastasis." (PMID 29993000, 2018). "Also, MYO10 mRNA expression was significantly higher in melanoma than in nevi in the Talantov melanoma data set." (PMID 29993000, 2018). "From these results, we speculated that Myo10 transports VASP to the tips of filopodia protruding from pseudopods in melanoma cells." (PMID 29993000, 2018). "Thus, we hypothesized that Myo10 localizes at the tips of filopodia projecting from pseudopods and mediates membrane dynamics at the leading edge of migrating melanoma cells." (PMID 29993000, 2018). "Thus, if the main target of the Pten/PIP3 signaling pathway is to activate Myo10 so that it induces pseudopod formation required for melanoma induction/metastasis, Myo10KO could diminish the PtenKO phenotype." (PMID 29993000, 2018). "There was a tendency for higher Myo10 expression in melanoma (n = 5, high; 3, medium; and 1, low) vs. nevi (n = 2, medium; and 3, low), but the sample number was not large enough to determine whether there was a statistical difference in expression levels between the two groups." (PMID 29993000, 2018).
melanoma (continued). "To investigate the expression of Myo10 in these induced melanoma, we performed immunoblot analysis of whole tumor lysates and found that only the WT mice expressed full-length Myo10, and neither WT nor mutant mice expressed headless Myo10." (PMID 29993000, 2018). "It is not clear whether Myo10 mediates the same mechanism in the progression of these types of cancer, but our findings in melanoma may provide a new direction to tackle other types of cancer." (PMID 29993000, 2018).
osteosarcoma (4 papers, 2019 to 2025). A usually aggressive malignant bone-forming mesenchymal neoplasm, predominantly affecting adolescents and young adults. "An earlier study supports this possibility and found α5 integrin can interact with Myo10 in U2-OS osteosarcoma cells." (PMID 35573666, 2022). "Additionally, circMYO10, a circular RNA derived from myosin X (MYO10) back-splicing, is upregulated in osteosarcoma cell lines." (PMID 40508066, 2025). "In addition, some potential downstream genes of miR-30b-3p, such as ATG5, PAK1, FOXP4, and MYO10 also exerted crucial roles in osteosarcoma." (PMID 35123530, 2022). "CircMYO10 is a circular RNA generated by back-splicing of gene MYO10 and is upregulated in osteosarcoma cell lines, but its functional role in osteosarcoma is still unknown." (PMID 31665067, 2019).
lung squamous cell carcinoma (3 papers, 2018 to 2023). "MYO10 is found to be upregulated in many humor cancers and correlated with poor prognosis, such as lung squamous cell carcinoma and cervical cancer." (PMID 36645718, 2023). "We showed that the MYO10 mRNA expression ratio can be used as an independent prognostic factor for survival of patients with resected lung squamous cell carcinoma and propose that MYO10 may represent a new molecular target for therapeutic intervention." (PMID 29934580, 2018).
prostate carcinoma (3 papers, 2018 to 2023). A carcinoma that arises from epithelial cells of the prostate gland. "Myo10 and Myo1b are both expressed at higher levels in prostate cancer cells with high metastatic potential and in metastatic prostate cancer tissues." (PMID 35853101, 2022).
glioma (2 papers, 2021 to 2024). A benign or malignant brain and spinal cord tumor that arises from glial cells (astrocytes, oligodendrocytes, ependymal cells). "Our study detected two rare germline variants, c.4448A>G (N1483S) and c.1511C>T (A504V), of MYO10 in the familial glioma cohort." (PMID 38773237, 2024). "The heatmap of the PSI data of these nine AS events in glioma samples show that eight AS events are down-regulated in the high-risk subtype while the MYO10|71604|AT is up-regulated in high-risk subtype." (PMID 34055619, 2021). "In addition to MYO10 c.745C>T (R249X), five other somatic MYO10 frameshift or missense mutations were detected in the Finnish familial glioma tumor cohort." (PMID 38773237, 2024). "Interestingly, somatic MYO10 mutations were observed in tumors of familial glioma patients, further supporting the role of MYO10 in tumor development." (PMID 38773237, 2024). "The known glioma risk variant rs55705857 in CCDC26 was co-inherited together with rare variants in GALNT13, MYO10 or AR in three out of six families carrying these rare variants, and it was also detected in affected cases in three additional families." (PMID 38773237, 2024). "When considering the rate, inheritance pattern, and population frequencies of detected rare, damaging coding variants in MYO10, AR and GALNT13, enhancer-linked risk variant in CCDC26, and other detected risk variants, our results suggest polygenic inheritance of familial glioma in Finland." (PMID 38773237, 2024).
Insulin resistance (2 papers, 2013 to 2023). Increased resistance towards insulin, that is, diminished effectiveness of insulin in reducing blood glucose levels. "Combined with their potential role in glucose metabolism and insulin resistance, such evidence suggests that MYO10 and ADGRL3 could be related to the underlying mechanisms of the comorbidity of PCOS in epilepsy." (PMID 40217327, 2023). "Variants of genes AKAP6, NPAS3, MARCH6 and FBXL7 have been previously reported to be associated with insulin resistance, inflammatory markers or adiposity studies using genome-wide approaches whereas associations of CDH18 and MYO10 with MetS traits have not been reported before." (PMID 23628382, 2013).
lung adenocarcinoma (2 papers, 2013 to 2022). A carcinoma that arises from the lung and is characterized by the presence of malignant glandular epithelial cells. "We have discovered ATP6V1C1, MYBBP1A, MACF1 and MYO10 upregulation in lung adenocarcinoma and accordingly, it is concluded that these genes have an important role in lung adenocarcinoma metastasis and we have reported all the mentioned genes for the first time in lung adenocarcinoma." (PMID 23874428, 2013).
lymph node metastasis (2 papers, 2015 to 2022). "This notion was further supported by our 2-year follow-up and we found that patients with higher Myosin X expression had increased risk of lymph node metastasis in patients with LSCC." (PMID 35951144, 2022). "Our findings that elevated MYO10 expression in NSCLC patients was associated with lymph node metastasis led us to hypothesise that MYO10 might be involved with cell motility." (PMID 25749519, 2015). "To determine the clinical significance and underlying role of Myosin X in LSCC, we made a 2-year follow-up and analyzed the correlations between the expression of Myosin X and lymph node metastasis." (PMID 35951144, 2022). "We found that increased Myosin X expression correlated with lymph node metastasis in LSCC (P < 0.001)." (PMID 35951144, 2022).
metastatic tumors (2 papers, 2020 to 2023). "In PCa, Myo1b, Myo6, Myo9b, Myo10, and Myo18a were expressed at higher levels in high metastatic potential cells, and especially Myo1b and Myo10 were expressed at higher levels in metastatic tumors." (PMID 33292248, 2020). "The motor protein myosin-X (MYO10) is significantly up regulated in metastatic tumors." (PMID 37098542, 2023).
Aleutian disease (1 paper, 2024). "From this, we identified several candidate genes contributing to the growth and feed efficiency (ARID1B, APPL1, TOX, and GPC5), reproduction (GRM1, RNASE10, WNT3, WNT3A, and WNT9B), pelt quality (MYO10, and LIMS1), and Aleutian disease tests (IFNGR2, APEX1, UBE3A, and STX11)." (PMID 38167844, 2024).